KIF14 (kinesin family member 14)
Diseases named in the same sentence as KIF14 in open-access papers (continued):
Sharing a sentence is not in itself a finding about the gene and the disease.
breast carcinoma (continued). "KIF14 or KIF11 are overexpressed in multiple tumor types including ovarian cancer, breast cancer, and EC." (PMID 40075652, 2025). "Recently, KIF14 has been reported to regulate the PI3K/AKT pathway by upregulating the phosphorylation of AKT and contribute to chemoresistance in breast cancer." (PMID 33203790, 2020). "Elevated expression levels of kinesins KIF14, KIF4A, KIF20A, and KIF23, KIF2C, and KIFC1 have been reported in breast cancer cell lines, other kinesins KIF10, KIF18A, and KIF15 have been linked to prognostic indicators in breast cancer patients." (PMID 32346924, 2020). "The underlying mechanism most likely consists of the joint involvement of KIF14- and Mieap-positive cells as well as EZR-negative cells in the realization of breast cancer invasion." (PMID 32679794, 2020). "KIF2A, KIF14 and KIF26B were found overexpressed in lymph nodes-positive breast cancer patients indicating putative impacts on tumor metastasis." (PMID 32322170, 2020). "While the breast cancer candidacy of CENPF, KIF14, NEK2, DTL, CKS1B, ASPM and EXO1 genes have been identified earlier, there is only one prominent report indicating the candidacy of EXO1 in breast cancers and remains to be investigated." (PMID 24147022, 2013). "Four showed centrosome amplification (KIAA0101, KIF14, KIF23 and HMMR) on the HeLa cell line and the breast cancer cell line Hs578T." (PMID 22956898, 2012). "It is also unclear if KIF14- and Mieap-positive and EZR-negative cells interact with each other in torpedo-like structures and whether their cooperation is needed for breast cancer invasion and metastasis." (PMID 32679794, 2020). "Our results indicate that positive expression of KIF14 and Mieap and negative expression of EZR at the tips of the torpedo-like structures are significantly associated with breast cancer metastasis." (PMID 32679794, 2020). "Our results indicate that the positive expression of KIF14 and Mieap and negative expression of EZR at the tips of the torpedo-like structures is associated with a high frequency of breast cancer metastasis." (PMID 32679794, 2020). "In other words, KIF14, Mieap, and EZR can be considered as markers of breast cancer invasion." (PMID 32679794, 2020). "In addition, KIF14-positive cells show upregulation of the THBS4 (thrombospondin 4) gene that is known to possess proangiogenic and proinflammatory activity in breast cancer." (PMID 32679794, 2020). "High frequency of metastases and decreased metastasis-free survival were detected in patients either with positive expression of KIF14 or Mieap or negative expression of EZR at the tips of the torpedo-like structures in breast cancers." (PMID 32679794, 2020). "Thus, the activity of KIF14, Mieap, and EZR at the tips of the torpedo-like structures predetermines the metastatic potential of breast cancer and KIF14- and Mieap-positive and EZR-negative tumor cells are most likely potential metastasis-initiating cells." (PMID 32679794, 2020). "In conclusion, the positive expression of KIF14 and Mieap and negative expression of EZR at the tips of the torpedo-like structures are associated with breast cancer metastasis." (PMID 32679794, 2020). "Unlike CENPE, KIF14 acts as an oncogene in various cancers, including lung cancers, ovarian cancers, breast cancers and adult gliomas." (PMID 26933822, 2016). "The KIF14 (Kinesin 14) (13-fold) is an oncogene related to several cancers and where mRNA overexpression is a negative prognostic factor in lung and breast cancer." (PMID 22905093, 2012). "In total, positive expression of KIF14 and Mieap and negative expression of EZR were observed in 58.4 (45/77), 45.4% (35/77), and 59.2% (45/76) of breast cancers, respectively." (PMID 32679794, 2020). "In addition, research in vitro is required to confirm whether positive expression of KIF14 and Mieap, as well as negative expression of EZR, are critical for breast cancer migration and invasion." (PMID 32679794, 2020).
lung carcinoma (21 papers, 2010 to 2025). "Consistent with an oncogenic role, KIF14 is located within a minimal common region of DNA amplification on chromosome 1q that occurs in ~21% of lung cancers and is positively associated with tumour progression and metastasis in LUSC." (PMID 40002279, 2025). "Numerous studies have correlated KIF18B with the proliferation, migration and invasion of cancer cells, whereas KIF14 has been implicated in the development of gastric, colorectal and lung cancers." (PMID 38494845, 2024). "Recent studies have focused on the role of kinesin proteins, such as KIF3, KIF5B and KIF14, in lung cancer progression; however, the detailed mechanisms underlying the functions of these proteins remain unclear." (PMID 23626713, 2013). "Taken together, these results suggest that a KIF14 deficiency might promote aneuploidy, resulting in tumor formation, and that KIF14 might act as a tumor suppressor in lung cancer." (PMID 23626713, 2013). "As a molecular motor involved in cytokinesis, KIF14 serves as oncogene in numerous malignancies including cholangiocarcinoma, prostate, cervical, and lung cancers." (PMID 40374610, 2025). "Transcriptomic analyses identified KIF14 as a prognostic gene whose high expression was correlated with shorter survival times in lung cancer patients." (PMID 40002279, 2025). "While most studies indicate that KIF14 behaves as an oncogene, it has been described to have both oncogenic and tumour suppressive effects in lung cancer." (PMID 40002279, 2025). "Our results suggest that KIF14 acts as a tumor suppressor, which agrees with previous research in which it was shown that overexpression of KIF14 reduced cell proliferation in lung cancer." (PMID 40075652, 2025). "Similar to lung cancer, overexpression of KIF14 was also reported in several cancers, and the upregulation of this kinesin family member gene has been associated with poor prognosis." (PMID 36552262, 2022). "The mitotic kinesin KIF14 has been previously shown to be overexpressed in a variety of cancers, including lung cancer." (PMID 35464867, 2022). "Subsequent studies by the same group suggested that KIF14 messenger RNA expression was independently prognostic for outcome in lung cancer." (PMID 27128470, 2016). "The overexpression of KIF14 in lung cancer cells significantly inhibited anchorage-independent growth in vitro and xenograft tumor formation in vivo." (PMID 23626713, 2013). "Several kinetochore molecules were found in our signature and have already been described as prognostic markers in other tumours: KNTC2 in lung cancer and kinesin KIF14 in breast and lung cancer." (PMID 20885975, 2010). "KIF14 has been shown to be oncogenic in several studies and has been reported as a prognostic biomarker for several cancers, but its relative importance as a driver gene in lung cancer pathogenesis is yet to be clarified." (PMID 35620733, 2022). "Their results indicated that expression of KIF14 is an independent prognostic variable for DFS in lung cancer and they found that knocking down KIF14 expression decreases tumorigenicity in vitro, suggesting that KIF14 is a potentially important marker in lung cancer that warrants further study." (PMID 35464867, 2022).
retinoblastoma (18 papers, 2009 to 2025). A malignant tumor that originates in the nuclear layer of the retina. "Although DNA methylation typically suppresses gene expression, KIF14 is differentially methylated and overexpressed in retinoblastoma, suggesting complex epigenetic regulation." (PMID 41150792, 2025). "Overexpression of KIF14 accelerates murine retinoblastoma development through facilitating angiogenesis." (PMID 29706624, 2018). "The Simian Virus 40 T-antigen-driven retinoblastoma model is known to upregulate endogenous Kif14 during tumourigenesis." (PMID 30385851, 2018). "Genomic gain of KIF14 and overexpression of this protein have been observed in breast, retinoblastoma, liver, renal, lung and ovarian cancers, etc.." (PMID 27128470, 2016). "KIF14 has been found to be overexpressed due to genomic gain in multiple cancers, including breast, retinoblastoma, liver, renal, lung and ovarian cancers, etc.." (PMID 27128470, 2016). "KIF14 was first identified as an oncogene and a contributor to malignant transformation in the childhood cancer retinoblastoma." (PMID 24626475, 2014). "We quantified mRNA expression of candidate genes for proliferation (KIF14 and E2F3) in a large retinoblastoma tumor cohort and associated with disease phenotype." (PMID 19190782, 2009). "We recently crossed this Kif14 Tg mouse into a transgenic retinoblastoma mouse model." (PMID 30385851, 2018). "Its protein product, a mitotic kinesin, accelerates growth of normal mammary epithelial cells in vitro and retinoblastoma tumours in a mouse model, while KIF14 knockdown blocks growth of brain, liver, ovarian, breast, prostate, and other tumour cells and xenografts." (PMID 30385851, 2018). "Located on chromosome 1q32.1, genomic gain of KIF14 occurs in up to 50% of retinoblastomas." (PMID 24626475, 2014). "KIF14 and E2F3 mRNA expression was quantified by real time PCR in 57 retinoblastoma (RB) tumors, 3 RB cell lines, and control samples that included 4 each fetal, age-matched, adult retinas." (PMID 19190782, 2009).
gastric cancer (15 papers, 2017 to 2025). A primary or metastatic malignant neoplasm involving the stomach. "KIF14 promotes tumor progression and metastasis and acts as a predictor of poor prognosis in human gastric cancer." (PMID 37175004, 2023). "Similarly, studies have shown that in gastric cancer, when KIF14 mRNA is highly expressed, the prognosis is significantly lower than that with low KIF14 mRNA expression." (PMID 36341437, 2022). "Moreover, KIF14 silence led to diminished proliferation, invasion and migration of gastric cancer cells." (PMID 34605738, 2021). "For example, the expression of KIF14 was remarkably increased in gastric cancer tissues and cells." (PMID 34605738, 2021). "KIF14 is a potential oncogene, promotes gastric cancer progression and metastasis." (PMID 34733886, 2021). "KIF14 can promote tumor progression and serve as an independent biomarker in human gastric cancer." (PMID 34699322, 2021). "For instance, previous reports revealed that up-regulation of KIF14 could promote cancer progression and metastasis, and could predict poor prognosis in gastric cancer and colorectal cancer." (PMID 32536821, 2020). "In 64 pairs of AGC tissue samples and paired normal tissues obtained by our group, as well as GC cell lines, we also observed a significant upregulation of KIF14 in gastric cancer tissues and cell lines, which imply that KIF14 may serve as oncogene in GC development." (PMID 40374610, 2025). "However, KIF14 also regulates gastric cancer progression and metastasis via p-Akt." (PMID 38308202, 2024). "As a mitotic kinesin, KIF14 has been reported to serve oncogenic roles through the regulation of the cell cycle, DNA replication, and DNA repair biological processes in a variety of malignancies, such as colorectal cancer, ovarian cancer, gastric cancer, and prostate cancer." (PMID 34497684, 2021).
microcephaly (14 papers, 2018 to 2025). A congenital or acquired developmental disorder in which the circumference of the head is smaller than normal for the person's age and sex. "The KIF11 mutation was found in 75% of patients with microcephaly in clinical samples; KIF14 mutations have also been reported in patients." (PMID 40964093, 2025). "Loss of gene KIF14 leads to cytokinesis and developmental defects in Drosophila and to microcephaly and growth retardation in mice." (PMID 38515024, 2024). "Knockout mice lacking Kif14 product exhibit severe microcephaly; recently, exome-sequencing analysis identified microcephaly-causing variants of KIF14." (PMID 33946187, 2021). "In particular, KIF14 is fundamental for brain development: a fetus with KIF14 mutations presented microcephaly with a flattened forehead, strong delay in the development of the telencephalon, and hypoplasia of the cerebellum." (PMID 34663805, 2021). "This is made evident by human and mouse mutations of abscission genes that cause forms of microcephaly: Cep55, Kif20A, Kif20B, Kif14, CitK, and Sept7." (PMID 36303610, 2021). "Similarly, disruption of the MB protein Kif14 is associated with microcephaly and kidney defects in human and zebrafish, but only with microcephaly in the mouse." (PMID 32269212, 2020). "KIF14 (OMIM ID: 611279) and CEP55 (OMIM ID: 610000), like CIT, are recessively inherited etiologies of microcephaly, whereas variants in PPP1R12A (OMIM ID: 602021) are responsible for a de novo dominant form of a holoprosencephaly spectrum that includes individuals with microcephaly." (PMID 39316437, 2024). "Furthermore, the codon based site models revealed an inconsistent signature of pervasive positive selection in primates for all of the microcephaly genes analyzed in the present study except KIF14." (PMID 33941077, 2021). "Thus far, three of them, CEP55, KIF14, and CITK, have been associated with specific human microcephaly syndromes." (PMID 36303610, 2021). "We observed one single m6A site near the stop codon in 7 microcephaly-related E-SMRs, including Brca2, Cep152, Ddx11, Nde1, Kif14, Stil and Cdk5rap2, 3 polymicrogyria-related E-SMRs (Eomes/Tbr2, Pax6 and Foxp2), and 3 megalencephaly-related E-SMRs (Gli3, Ccnd2 and Kif7)." (PMID 32992647, 2020).
colorectal cancer (13 papers, 2019 to 2025). A primary or metastatic malignant neoplasm that affects the colon or rectum. "For example, studies in colorectal cancer have shown that low KIF14 expression is associated with advanced disease and poor prognosis, supporting its role as a favorable prognostic marker in certain tumor contexts." (PMID 40075652, 2025). "Like our results, low expression of KIF14 mRNA has been related to worse overall survival in lung adenocarcinoma and colorectal cancer." (PMID 38016355, 2024). "For instance, KIF14 was found to be upregulated in colorectal cancer, and its overexpression accelerated colorectal tumorigenesis." (PMID 35156510, 2022). "In turn, KIF14 mRNA expression was upregulated in tumors compared to normal tissues, which is in line with the previous reports on various cancers, including colorectal cancer." (PMID 34575892, 2021). "In summary, we first reported the high expression of UTX in colorectal cancer and found its regulation of KIF14 expression." (PMID 31139021, 2019). "More recently, KIF14 was found to promote cell proliferation via the activation of AKT in colorectal cancer." (PMID 31139021, 2019). "Recently, KIF14 was found to promote cell proliferation via the activation of AKT in colorectal cancer." (PMID 31139021, 2019). "Additionally, in colorectal cancer (CRC), studies have demonstrated that altered expression levels of KIF11 and KIF14 are associated with patient outcomes." (PMID 40075652, 2025). "KIF14 was identified as an oncogene in retinoblastoma, ovarian cancer, and colorectal cancer." (PMID 35156510, 2022). "To explore the mechanism of KIF14 in promoting CC onset, we analyzed the signaling pathway through GSEA and found that the cell cycle signaling pathway was closely related to KIF14, which was similar to the results reported for hepatocellular carcinoma, prostate cancer, and colorectal cancer." (PMID 34495250, 2021). "Whether UTY also promotes the development of colorectal cancer by participating in the regulation of KIF14 expression requires further research." (PMID 31139021, 2019). "KIF14 expression was shown to promote the proliferation of colorectal cancer cells." (PMID 31139021, 2019). "We also observed that the KIF14 protein levels were significantly increased in the TNBC cells and to an even higher extent in the colorectal cancer cells." (PMID 39409999, 2024). "Here, we reported that UTX expression was elevated in human colorectal cancer and enhanced CRC cell proliferation by promoting the expression of KIF14." (PMID 31139021, 2019). "KIF14, KIF18B, KIF23, KIF4A, KNTC1, NCAPG2, and MCM3 regulate chromosomal integrity, mitotic spindle formation, and DNA replication, processes that are frequently dysregulated in colorectal cancer." (PMID 40405535, 2025).
ovarian carcinoma (11 papers, 2012 to 2024). A malignant neoplasm originating from the surface ovarian epithelium. "It has been reported that KIF14 is a marker of poor prognosis in patients with hepatocellular carcinoma and ovarian cancer, where KIF14 overexpression enhances tumor growth, while its knockdown decreases tumorigenicity in vitro and in xenografts." (PMID 28525372, 2017). "Our group and others have previously shown that KIF14 protein and mRNA are overexpressed in multiple cancers including ovarian cancers (OvCa tumors)." (PMID 24626475, 2014). "We have previously shown prognostic significance of KIF14 mRNA in breast, lung and ovarian cancers and uncovered transcriptional and epigenetic regulation of KIF14 overexpression in ovarian cancers." (PMID 25528264, 2014). "KIF14 has been identified as a prognostic marker in breast and ovarian cancer in gene expression profiling studies." (PMID 22956898, 2012). "Moreover, KIF14 levels are prognostic for the outcome of hepatocellular carcinoma and ovarian cancer, where KIF14 overexpression enhances tumor growth, while its knockdown decreases tumorigenicity in vitro and in xenografts." (PMID 28525372, 2017). "Located on chromosome 1q32, KIF14 has been demonstrated to be overexpressed at the genomic and gene expression levels in multiple cancers, including breast and retinoblastoma, liver, renal papillary, lung, and ovarian cancers (OvCas)." (PMID 25528264, 2014). "Previously, it has been shown that KIF14 mRNA is overexpressed in ovarian cancer (OvCa), regardless of histological subtype." (PMID 25528264, 2014).